CTNNB1 (catenin beta 1)
Diseases named in the same sentence as CTNNB1 in open-access papers (continued):
Sharing a sentence is not in itself a finding about the gene and the disease.
endometrial cancer (continued). "Mutations in the CTNNB1 gene of endometrial cancers are more common in the lower grades and early stages of disease development, and they are associated with a poorer disease outcome due to a higher chance of recurrence." (PMID 33915799, 2021). "Two studies demonstrated the role of the beta-catenin/CTNNB1 gene as a poor prognostic factor in low-risk endometrial cancer." (PMID 34485158, 2021). "Of the 125 endometrial carcinomas examined, 21 (16.8%) tumors carry exon 3 CTNNB1 mutations and concomitant nuclear expression of β-catenin." (PMID 33668727, 2021). "Researchers have found that CTNNB1 mutations can identify a subset of low grade, early stage endometrial cancer patients, which was also proved by our study." (PMID 30886832, 2019). "Lower CNA numbers have been detected in CASP8-mutated oral squamous cell carcinoma and in CTNNB1-mutated endometrial cancer." (PMID 27831464, 2016). "Additional work is needed to identify the mechanistic basis and biological significance of the mutual exclusivity of KRAS and CTNNB1 mutations in endometrial cancer." (PMID 22383975, 2012). "Endometrioid endometrial carcinomas with CTNNB1 mutations are characteristically early stage tumors associated with favorable prognosis." (PMID 20368795, 2010). "As research continues to uncover the full impact of CTNNB1 mutations on endometrial cancer biology, they may also emerge as valuable targets for novel therapeutic strategies aimed at improving the outcomes of patients with these aggressive tumors." (PMID 40072110, 2025). "As research advances, the integration of CTNNB1 mutation status into clinical practice holds promise for improving personalized treatment strategies for endometrial cancers, particularly when used alongside multi-targeted approaches and comprehensive biomarker panels." (PMID 40072110, 2025). "In contrast, strong nuclear β-catenin localization, typically associated with overall overexpression, serves as a reliable indicator of β-catenin activation in AH/EIN or endometrial carcinoma, demonstrating ≥90% specificity and sensitivity for CTNNB1 mutations." (PMID 38539494, 2024). "However, only half of these APC mutations give rise to truncated proteins; therefore, CTNNB1 mutations are likely to be the dominant WNT-activating mutation in endometrial cancer." (PMID 37048063, 2023). "Both APC and CTNNB1 are mutated in approximately 12% and 30% of endometrial cancers, respectively." (PMID 37048063, 2023). "To investigate whether the endometrial cancer in subject #39 originated from the cell clone with the CTNNB1 mutation (c.109T > G) detected in the initial LBC screening, we carried out genetic analysis of her cancer tissue." (PMID 39516270, 2023). "In this comprehensive analysis of 648 high-risk EC, we evaluated the prognostic value of ER, PR, L1CAM and CTNNB1 mutations and established clinicopathologic and molecular risk factors in one of the largest cohorts of molecularly classified high-risk endometrial cancers worldwide." (PMID 36690721, 2023). "Taken together, these studies suggest that defining endometrial cancers by both molecular characteristics and clinicopathologic features is a more effective way to assess risk factor and treatment options, particularly in the case of CTNNB1 mutations." (PMID 36248967, 2022). "Copy number low microsatellite stable endometrial cancer had unusually high CTNNB1 mutation." (PMID 36358604, 2022). "This begs the question of how CTNNB1 mutations found in endometrial carcinoma may affect β-catenin at the membrane as well as in the cytoplasm." (PMID 36248967, 2022). "A recent study including 81 women with endometrial cancer has shown that the incidence of CTNNB1 somatic gene mutation was higher in early onset endometrial cancer and the immunohistochemical accumulation of beta-catenin was inversely correlated with patients’ age." (PMID 33546293, 2021).
endometrial cancer (continued). "However, mutation of APC (Adenomatous polyposis coli) or CTNNB1 (the gene that encodes β-catenin) is rare in endometrial cancer, indicating that other mechanisms are responsible for the aberrant activation of β-catenin." (PMID 34068065, 2021). "Furthermore, 46% of the CTNNB1 mutations in endometrial cancer were reported to be immediately phosphorylated by glycogen synthase kinase-3 (GSK-3β)." (PMID 34836311, 2021). "Between 10% and 45% of endometrial cancers have missense mutations of CTNNB1." (PMID 34068065, 2021). "Another candidate that has not yet been evaluated is LEF1, a nuclear effector of the Wnt/beta-catenin pathway, overexpressed in CTNNB1-mutated tumours according to the Clinical Proteomic Tumour Analysis Consortium (CPTAC) proteogenomic characterisation of endometrial cancer." (PMID 34420090, 2021). "In liver and endometrial cancer, CTNNB1 mutations are common while APC mutations are rare." (PMID 32751567, 2020). "Although mutation of CTNNB1 is rare in BC, mounting evidence has revealed that the mutations in CTNNB1 are often associated with an upregulation of β-catenin and the pathogenesis of endometrial cancer and ovarian cancer." (PMID 30181805, 2018). "Although somatic mutation of CTNNB1 is rare in BC, mounting evidences have revealed that the somatic mutations in CTNNB1 are often associated with the upregulation of β-catenin and the pathogenesis of endometrioid-type of endometrial cancer and ovarian cancer." (PMID 26285011, 2015). "According to various reports, 10 to 45% of endometrial cancers present missense mutation of CTNNB1." (PMID 26366420, 2015). "Mutations of β-catenin gene (CTNNB1) were found in many endometrial cancers." (PMID 26366420, 2015). "One finding that may have implications for understanding the biology underlying endometrial cancer is the hereto-unrecognized mutual exclusivity of CTNNB1 and KRAS mutations in this cohort." (PMID 22383975, 2012). "Further study identified β-catenin capacity as an immunohistochemical surrogate of CTNNB1 exon 3 mutations, showing that β-catenin expression, particularly the nuclear expression possesses a good prognostic factor for endometrial carcinoma and may reflect the mutation of CTNNB1 gene." (PMID 38008739, 2023). "A systematic review of fifteen observational studies with 1158 endometrial carcinomas showed that the nuclear expression of β-catenin is an accurate immunohistochemical surrogate of CTNNB1 exon 3 mutations and thus might be considered in the endometrial cancer risk stratification." (PMID 36292090, 2022). "This suggests CTNNB1 mutations may drive endometrial cancer progression." (PMID 36248967, 2022). "In endometrial cancer, ELF4, acting as a transcriptional activator, is recruited to the promoter of catenin beta 1 (CTNNB1; encoding β-catenin) by tribbles pseudokinase 3 (TRIB3), thereby enhancing oncogenesis and self-renewal of cancer stem cells." (PMID 40083328, 2025). "CNL endometrial carcinomas are typically associated with mutations in genes such as PTEN, PIK3CA, and CTNNB1." (PMID 40004914, 2025). "In Black patients, CTNNB1 mutations were more frequent in NSCLC, but less frequent in endometrial cancers." (PMID 38297963, 2024). "Patients with endometrial cancer also had high prevalence of variants in PTEN (52.0%), CTNNB1 (15.6%), and RNF43 (10.5%) genes." (PMID 39277826, 2024). "In AH/EIN, the most commonly mutated genes, including PTEN, CTNNB1, ARID1A, PIK3CA, and KRAS, are also mutated in endometrial carcinoma." (PMID 38539494, 2024). "Whilst APC mutations give rise to truncated proteins, particularly in CRC, CTNNB1-activating mutations give rise to stabilized β-catenin through point mutations in HCC, endometrial cancer, and pancreatic cancer." (PMID 37048063, 2023). "In the TCGA cohort of 240 endometrial cancer cases, alterations in CTNNB1 or APC genes were observed to be 30% or 12%." (PMID 37655825, 2023).
endometrial cancer (continued). "In a previous work by our group, we investigated the prognostic role of additional biomarkers (ARID1A and CTNNB1) in endometrial carcinoma in a subset of the analyzed cohort showing the relevance of an improved surrogate molecular classification." (PMID 37064027, 2023). "Given the prognostic value of exon 3 CTNNB1 mutations in EEC, some have suggested a modification to the TCGA molecular classification of endometrial cancer." (PMID 36248967, 2022). "Altered Wnt/β‐catenin signaling, as a result of gene alterations such as those found in APC or in CTNNB1 (β‐catenin), has been reported to drive tumorigenesis in numerous tumors including endometrial cancer." (PMID 34318590, 2022). "Aberrant expression of CTNNB1 is found in uterine fibroids, endometrial hyperplasia, and endometrial cancer." (PMID 36077170, 2022). "CTNNB1, a known endometrial cancer stem cell marker, was upregulated in HHUA-SP-derived tumors compared to non-SP HHUA-derived tumors." (PMID 35659728, 2022). "We found two cases of low-grade endometrioid carcinoma with altered CTNNB1 that is thought to show prognostic significance with worsen recurrence-free survival in early-stage low-grade endometrial carcinoma." (PMID 36010253, 2022). "This study found that 45/53 (85%) of CTNNB1 mutant endometrial cancers had nuclear β-catenin localization." (PMID 34068065, 2021). "Especially in young patients, there are propositions of establishing CTNNB1 status as the 5th molecular classifier of endometrial cancer." (PMID 33546293, 2021). "The other major alteration reported in endometrial cancers is nuclear accumulation of β-catenin (CTNNB1)." (PMID 34068065, 2021). "At the molecular level, type I endometrial cancer is associated with mutations in genes such as PTEN, KRAS, ARID1A, PIK3CA, and CTNNB1 and microsatellite instability (MSI)." (PMID 34565373, 2021). "Another study explored the impact of ARID1A and CTNNB1/-catenin alterations in a group of molecularly classified endometrium cancers using targeted next-generation sequencing (NGS)." (PMID 34068065, 2021). "Since CTNNB1 mutations are found in about half of NSMP EECs, the CTNNB1-mutant group would account for about 20% of all endometrial carcinomas." (PMID 34073635, 2021). "The NSMP group predominantly consists of low-grade endometrioid-type endometrial carcinomas characterized by alterations in PI3K/AKT and WNT/β-catenin signaling pathways with relatively frequent mutations in exon 3 of CTNNB1 (52%)." (PMID 33668727, 2021). "Nuclear localization of β-catenin in neoplastic cells varies between 5% and 60% in CTNNB1 mutant endometrial carcinomas (mean 19.8%)." (PMID 34068065, 2021). "These endometrial cancers showed common mutation profiles, including PTEN, CTNNB1, PIK3CA, and PIK3R1 mutations." (PMID 32652986, 2020). "A total of 49 FFPE and LBC specimens (n = 24) were analyzed, revealing characteristic mutations for endometrial cancer, including PTEN, CTNNB1, PIK3CA, and PIK3R1 mutations." (PMID 32652986, 2020). "Most molecular studies in endometrial cancer have focused on the most common form, uterine endometrioid carcinoma (UEC), which is primarily driven by PTEN loss and mutations in FGFR2, ARID1A, CTNNB1, PIK3CA, PIK2R1, and KRAS." (PMID 26170901, 2015). "Mutations in KRAS and/or CTNNB1, GSK-3β, and APC gene are recognized as major alterations in type I endometrial cancer." (PMID 26366420, 2015).
endometrial cancer (continued). "Mutations in multiple oncogenes including KRAS, CTNNB1, PIK3CA and FGFR2 have been identified in endometrial cancer." (PMID 22383975, 2012). "In our study, we demonstrate that the differential expression of miRNAs exists even between endometrial carcinomas with and without CTNNB1 mutations." (PMID 37958433, 2023). "In our study, those endometrial cancers with an ARID1A mutation showed elevated levels of TILs and PD-L1 scores, and in contrast, cases with CTNNB1 mutated showed low levels of these two biomarkers, which would support this hypothesis." (PMID 36010253, 2022). "Furthermore, in endometrial cancer, RNF43 and CTNNB1 mutations are regularly detected, with CTNNB1 mutations being associated with aggressive cancers and poor survival." (PMID 35327645, 2022). "Taken together, these findings suggest that total nuclear β-catenin may not be as important as previously thought in driving the poor prognosis seen in CTNNB1-mutant endometrial cancers as other cellular components may also help activate the Wnt pathway." (PMID 34068065, 2021). "Many studies show that CTNNB1 mutation is primarily detected in endometrioid endometrial cancer rather than nonendometrioid endometrial carcinoma cases (NEEC)." (PMID 34068065, 2021). "On this account, it has been proposed that CTNNB1-mutant cases might constitute the fifth molecular group of endometrial carcinoma." (PMID 34073635, 2021). "The only site with a notably higher CTNNB1 mutation prevalence than other sites, endometrial cancer, is not a form of cancer that is especially likely to metastasize, relative to other sites." (PMID 29156750, 2017). "Thus, the presence of CTNNB1 mutations in endometrial carcinoma appears to be a negative prognostic factor." (PMID 38539494, 2024). "Thus, in endometrial carcinoma, it seems that CTNNB1 mutations, rather than APC mutations act as direct drivers rather than passengers." (PMID 37655825, 2023). "Since several other proteins, including S100P, are regulatory components of a novel ubiquitinylation complex involved in β-catenin degradation, further studies are in need with specific regard to trigger for β-catenin nuclear localization in endometrial cancer in the absence of CTNNB1 mutations." (PMID 36292090, 2022). "Additionally, they compared endometrial carcinoma cases with or without exon 3 CTNNB1 mutations and β-catenin staining patterns." (PMID 36248967, 2022). "Notably, a similar protective effect of CTNNB1 mutations has also been observed in endometrial carcinoma, indicating this may not be specific to NSCLC." (PMID 40768678, 2025). "Dysregulation of the phosphatidylinositol 3-kinase (PI3K) pathway, mitogen-activated protein kinase (MAPK) pathway, catenin beta 1 (CTNNB1), or AT-rich interaction domain 1A (ARID1A or BAF250) appears common in endometrial cancer patients." (PMID 35269532, 2022). "On the contrary, in non-inmunogenic endometrial cancer, recent studies have associated alterations such as CTNNB1 or PIK3CA genomic aberrations and CMYC amplification, with a low neoantigen load, that could lead to predict poor effects of immunotherapy response." (PMID 36010253, 2022). "In ovarian cancer, the most frequent actionable targets identified were ER (41%), PD1 (16.7%), and EFGR (11.5%), whereas in endometrial cancer, ER (58.7%), PTEN (58.7%), and CTNNB1 (19.6%) were more common." (PMID 30848097, 2019).
endometrial cancer (continued). "This study investigates the feasibility and the prognostic impact of the novel surrogate TCGA molecular classification of endometrial carcinoma into the clinical setting proposing an immuno-molecular algorithm supplemented with ARID1A and CTNNB1/β-catenin analysis." (PMID 33668727, 2021). "Both CTNNB1 alterations were exclusively detected in non-serous type cancer: one in clear-cell OC and the other in a case with simultaneous endometrioid ovarian and endometrial cancer." (PMID 36982928, 2023). "The CTNNB1 gene as well as the hair matrix cells seem to be preferentially targeted by the unknown genetic defect as pilomatricoma is a rare benign neoplasm and other potential CTNNB1 driven neoplasms do not seem to be more frequent in DM1 patients with the exception of endometrial cancer." (PMID 32155193, 2020). "Importantly, we found that the CTNNB1-enriched subgroup harbored frequent PTEN mutations but not for KRAS mutations, suggesting that PTEN loss but not KRAS mutations might enhance the CTNNB1-induced genetic program to promote tumor development in endometrial cancer." (PMID 26431491, 2015).